TIE1 (tyrosine kinase with immunoglobulin like and EGF like domains 1)
Diseases named in the same sentence as TIE1 in open-access papers (continued):
Sharing a sentence is not in itself a finding about the gene and the disease.
ovarian carcinoma (8 papers, 2018 to 2024). A malignant neoplasm originating from the surface ovarian epithelium. "Consistent with our results, it has been indicated that elevated TIE1 expression is associated with a poor prognosis in patients with gastric cancer, ovarian cancer and metastatic breast cancer 30-32." (PMID 38617545, 2024). "We also examined the association between TIE-1 expression and cisplatin resistance in 3 paired ovarian cancer cell lines." (PMID 30181600, 2018). "In women with primary serous ovarian malignancies, low epithelial expression levels of Tie-1 were significantly associated with a recurrence of ovarian cancer (p = 0.025), with a greater residual tumor size (>1cm) after primary surgery (p = 0.008) and with high grade tumors (p = 0.006)." (PMID 33151982, 2020). "Furthermore, low expression levels of Ang-2 and Tie-1 in ovarian cancer cells were linked to an aggressive phenotype of ovarian cancer cells." (PMID 33151982, 2020). "TIE1 is found to mediate platinum resistance in ovarian cancer cells through nucleotide excision repair." (PMID 36814284, 2023). "In ovarian cancer, TIE1 promotes XPC-dependent nucleotide excision repair (NER) to render platinum reagents resistance." (PMID 36814284, 2023). "We next investigated the effect of TIE-1 knockdown on cell growth using multiple ovarian-cancer cell lines." (PMID 32604863, 2020). "In this study, we performed immunohistochemical evaluation of Ang-2, Tie-1 and Tie-2 receptors in primary ovarian epithelial cancer tissue samples of 86 women and further in 16 related metastatic tumors." (PMID 33151982, 2020). "Expressions of Ang-2 and its receptors Tie-1 and Tie-2 in primary ovarian cancer and 16 high grade serous tumors with their related metastases." (PMID 33151982, 2020). "We previously reported that TIE-1 promotes DNA damage repair, thereby rendering ovarian-cancer cells resistant to cisplatin." (PMID 32604863, 2020). "Our findings demonstrated that TIE-1 inhibition selectively exhibited an antitumor effect by decreasing PI3K expression in high-PI3K-expressing ovarian-cancer cells." (PMID 32604863, 2020). "Our results suggested that TIE-1 regulates the PI3K/Akt pathway by increasing/decreasing PI3K expression in ovarian cancer." (PMID 32604863, 2020). "In summary, TIE-1 functions as a potential carcinogenic molecule by activating the PI3K/Akt signaling pathway in high-PI3K-expressing ovarian cancer." (PMID 32604863, 2020). "Overall survival (%) and hazard ratios (HR) of angiopoietin-2, Tie-1 and Tie-2 expressions of ovarian cancer patients." (PMID 33151982, 2020). "Taken together, our findings strongly implicate TIE-1 as a novel therapeutic target in high-PI3K-expressing ovarian-cancer cells." (PMID 32604863, 2020). "In summary, we demonstrated that TIE-1 is a key molecule involved in platinum resistance of ovarian cancer cells." (PMID 30181600, 2018). "We evaluated the effects of TIE-1 knock-down on the sensitivities of ovarian cancer cells to seven chemotherapeutic agents, which have different mechanisms of cancer cell killing." (PMID 30181600, 2018). "A public database analysis showed that high TIE-1 expression was correlated with a poor prognosis in ovarian cancer patients." (PMID 30181600, 2018). "Conversely enforced over-expression of TIE-1 was validated to decrease cisplatin sensitivity in multiple ovarian cancer cell lines and up-regulation of TIE-1 was correlated with poor prognosis and cisplatin resistance in patients with ovarian cancer." (PMID 30181600, 2018). "Reciprocally, we constructed a human TIE-1 expression vector and determined the effects of TIE-1 over-expression on chemo-sensitivities of ovarian cancer cells." (PMID 30181600, 2018). "We therefore propose that TIE-1 represents a promising therapeutic target for potentiating chemotherapeutic efficacy in patients with ovarian cancer." (PMID 30181600, 2018).
ovarian carcinoma (continued). "To determine the clinical significance of TIE-1 expression in ovarian cancer patients, we investigated the correlation between TIE-1 expression and patient prognosis." (PMID 30181600, 2018). "In the present study, we used genome-wide siRNA libraries covering over 6659 genes and identified tyrosine kinase with immunoglobulin-like and EGF-like domains 1 (TIE-1) as a novel gene mediating cisplatin resistance in ovarian cancer cells." (PMID 30181600, 2018). "More importantly, we found higher expression of TIE-1 in refractory stage III or IV ovarian cancer patients who had residual tumor on first surgery." (PMID 30181600, 2018). "TIE1 has been reported to be related to the PI3K/AKT signaling pathway in ovarian cancer." (PMID 36814284, 2023). "Moreover, TIE1 plays a critical role in ovarian cancer cell proliferation and growth by modulating the PI3K/AKT signaling pathway." (PMID 36814284, 2023). "Thus, in the present study, we investigated the tumor biological functions of TIE-1 in ovarian cancer." (PMID 32604863, 2020). "Moreover, in low-PI3K-expressing TOV112D ovarian-cancer cells, TIE-1 overexpression induced PI3K upregulation and promoted a PI3K-mediated cell proliferative phenotype." (PMID 32604863, 2020). "On the basis of the endogenous expression of PI3K in cells and/or whether TIE-1 knockdown induced cell-growth inhibition, we divided 11 ovarian-cancer cell lines into two groups: low-PI3K-expressing and high-PI3K-expressing cell lines." (PMID 32604863, 2020). "Accompanied with novel findings, TIE-1 could represent as a novel therapeutic target for platinum-resistant ovarian cancer." (PMID 30181600, 2018). "Our studies point to potential clinical significance of TIE-1 in ovarian cancer pathobiology." (PMID 30181600, 2018). "Importantly TIE-1 is proposed to represent a novel therapeutic target for potentiating chemotherapeutic efficacy in ovarian cancer, especially in patients with platinum-resistant cancer." (PMID 30181600, 2018). "Even in the group of patients with platinum-based chemotherapy (n = 1409), TIE-1 high expression was also significantly correlated with poor prognosis, suggesting a possible involvement of TIE-1 up-regulation in the acquisition of platinum resistance in ovarian cancer cells." (PMID 30181600, 2018). "Therefore, TIE-1 may function as an antiapoptotic regulator in high-PI3K-expressing ovarian-cancer cells." (PMID 32604863, 2020). "Therefore, the future development of specific TIE-1 inhibitors could be an effective strategy to improve the prognosis of ovarian-cancer patients." (PMID 32604863, 2020). "Their research clearly separates the functions of TIE-1 from TIE-2, revealing that TIE-1 overexpression correlates with poor prognosis and lower effectiveness of cisplatin in advanced ovarian cancer." (PMID 39138146, 2024). "However, TIE-1 pathobiology in ovarian cancer remains unknown." (PMID 30181600, 2018). "Overall, our results suggest that TIE-1 increases NER and DNA repair by up-regulating transcription of XPC, thereby rendering ovarian cancer cells resistant to DNA-adduct-type chemotherapeutic reagents." (PMID 30181600, 2018). "TIE-1 and PI3K p110α expression varied in the tested ovarian-cancer cell lines." (PMID 32604863, 2020). "The treatment of SKOV3 ovarian-cancer cells with siRNA against TIE-1 decreased the expression of key molecules in the PI3K/Akt signaling pathway, such as p110α and phospho-Akt, suggesting that TIE-1 is related to the PI3K/Akt pathway." (PMID 32604863, 2020). "The effect of TIE-1 inhibition depended on the high level of PI3K expression in ovarian-cancer cells, not histological types." (PMID 32604863, 2020). "Therefore, TIE-1 is suggested to promote XPC-dependent NER, rendering ovarian cancer cells resistant to platinum." (PMID 30181600, 2018).
ovarian carcinoma (continued). "Therefore, in the present study, we explore the biological significance of TIE-1 in the PI3K/Akt signaling pathway and demonstrate a novel molecular mechanism of action for TIE-1 in ovarian cancer, identifying TIE-1 as a target for the treatment of high-PI3K-expressing ovarian cancer." (PMID 32604863, 2020). "Furthermore, TIE-1 inhibition-induced PI3K downregulation did not affect low-PI3K-expressing ovarian-cancer or normal cells." (PMID 32604863, 2020).
gastric cancer (5 papers, 2017 to 2024). A primary or metastatic malignant neoplasm involving the stomach. "However, the precise mechanism underlying TIE1's involvement in Gastric Cancer (GC) remains elusive." (PMID 38706903, 2024). "Consistent with previous reports, a significant elevation of Tie1 expression was observed in stomach cancer (p = 3.49E‐5)." (PMID 28464467, 2017). "Elevated expression of Tie1 has been reported in some types of human cancer, such as stomach cancer." (PMID 28464467, 2017). "In gastric cancer, patients with Tie1 expression in their formalin-embedded tissue specimens had worse survival than the patients without Tie1 expression." (PMID 31340773, 2019). "In clinical practice, Tie1 expression shows a negative correlation with 5‐year survival rates in gastric cancer patients." (PMID 28464467, 2017).
diabetes (4 papers, 2018 to 2024). "Since angiogenesis is one of the key steps in the wound healing cascade, we measured Ang1/2 and Tie1/2 mRNA levels in the wound sections and found that diabetes-induced reduction in Ang1/2 and Tie1/2mRNA expression was rescued by MCS treatment." (PMID 30153276, 2018). "Diabetes was produced by injecting five consecutive low doses of STZ (50 mg/kg/day intraperitoneal (IP)) in 8-week-old GRECKO (GR;fl/fl Tie1 Cre+) and Cre− littermate controls (GRfl/fl) and GR;fl/flTie1 Cre+/Apoe−/− (DKO) mice and Cre− littermates (GR;fl/flApoe−/−)." (PMID 33888696, 2021).
Arthritis (3 papers, 2008 to 2024). Inflammation of a joint. "We have previously reported that expression of Ang-1, Ang-2, tyrosine kinase with immunoglobulin-like and EGF-like domains (Tie)-1 and Tie-2 increases as arthritis progressed, peaking on day 8 of disease." (PMID 22817681, 2012). "We also observed for the first time that ASV corresponding to Tie1 significantly reduced arthritis severity and joint destruction." (PMID 18593464, 2008). "The present study shows that unique ASV derived from receptors that play key roles in angiogenesis – namely, VEGF receptor type 1 and, for the first time, Tie1 – can markedly reduce arthritis severity." (PMID 18593464, 2008). "While expression of Ang-1 and of Tie receptors has been reported in RA, this is the first demonstration that Tie1 is effective in an in vivo model of arthritis." (PMID 18593464, 2008). "Importantly, ASV derived from VEGF receptor type 1 and Tie1, and to a lesser extent from VEGF receptor type 2 and fibroblast growth factor receptor 1, reduced clinical signs of arthritis in vivo." (PMID 18593464, 2008).
primary lymphedema (3 papers, 2022 to 2024). A congenital condition that results in swelling in the arms or legs, and can occur during adolescence or adulthood. "Genetic, structural, biochemical, and functional analysis of endothelial receptor tyrosine kinase TIE1 variants in patients reveals that TIE1 loss-of-function alleles cause late-onset primary lymphedema." (PMID 38820174, 2024). "Interestingly, mutations in Ang2 and genetic variants of Tie1 were recently associated with primary lymphedema in humans." (PMID 35763346, 2022). "A more profound understanding of Ang2 and Tie1 signaling should be of clinical interest, as Ang2 mutations were already implicated in human primary lymphedema, and Tie1 may follow suit." (PMID 35763346, 2022). "Prior studies have identified mutations in piezo-type mechanosensitive ion channel component 1 (PIEZO1), angiopoietin 2 (ANGPT2), and tyrosine kinase with Ig-like and EGF-like domains 1 (TIE1) in patients with primary lymphedema." (PMID 38747287, 2024).
breast tumors (2 papers, 2021 to 2025). "Collectively, these results support the hypothesis that TIE1 is cleaved in vivo, leading to activation of the AKT–p70S6K signaling pathway and contributing to enhanced cell survival in primary breast tumors." (PMID 41235901, 2025).
cervical cancer (2 papers, 2021 to 2024). A primary or metastatic malignant neoplasm involving the cervix. "Additionally, TIE1 has been shown to be associated with a poor prognosis in cervical cancer." (PMID 38617545, 2024). "Similarly, novel drugs that disrupt the TIE1-Basigin association could be developed as new agents for cervical cancer treatment." (PMID 38617545, 2024). "So, we conducted a Western blotting experiment, confirming that TIE1 can activate MAPK/ERK pathway in cervical cancer cells." (PMID 38617545, 2024). "TIE1 overexpression promoted the proliferation, migration and invasion of cervical cancer cells in vitro, as well as tumor growth and metastasis in vivo." (PMID 38617545, 2024). "Compared to that in normal cervical epithelium, TIE1 expression was higher in cervical cancer epithelial cells." (PMID 38617545, 2024). "We also performed univariate and multivariate Cox regression analysis to assess the prognostic value of TIE1 in cervical cancer." (PMID 38617545, 2024). "To further verify that TIE1 promoted cervical cancer progression by regulating Basigin, we applied siRNA or an inhibitor (AC-73) of Basigin to TIE1-overexpressing HeLa and SiHa cell lines." (PMID 38617545, 2024). "Collectively, these data revealed that TIE1 promotes cervical cancer progression in vitro and in vivo." (PMID 38617545, 2024). "To investigate the role of TIE1 in cervical cancer progression, we demonstrated TIE1 was significantly overexpressed in cervical cancer cell lines compared to normal cervical cell line H8 using Western blotting." (PMID 38617545, 2024). "To further explore the association between clinicopathological factors and TIE1 expression, we examined the level of TIE1 in 135 cervical cancer patients by IHC." (PMID 38617545, 2024). "In summary, our study provides compelling evidence that high TIE1 expression is clinically and functionally significant in the progression of cervical cancer; TIE1 acts by stabilizing Basigin and increasing MMPs levels." (PMID 38617545, 2024). "While measuring MMP-2 and MMP-9 activities would undoubtedly provide valuable insights, our current investigation focuses on understanding TIE1's broader impact on the cervical cancer progression." (PMID 38617545, 2024). "Our findings revealed that, as the severity of cervical lesions increased, the level of serum Tie-1 gradually increased, and that sTie-1 levels can effectively distinguish cervical cancer patients from healthy controls." (PMID 34975347, 2021). "Our previous study demonstrated elevated TIE1 expression in cervical cancer cells." (PMID 38617545, 2024). "Furthermore, we used a lentiviral vector to construct SiHa and HeLa cervical cancer cell lines that stably overexpressed FLAG-tagged TIE1." (PMID 38617545, 2024). "Our functional assays demonstrated that TIE1 promoted cervical cancer growth and metastasis." (PMID 38617545, 2024). "We found that TIE1 was upregulated in human cervical cancer and correlated with a poor prognosis." (PMID 38617545, 2024). "Thus, we identified TIE1 as a prognostic factor and provided a powerful molecular basis for TIE1-mediated anti-cervical cancer therapy." (PMID 38617545, 2024). "In summary, Basigin is an essential factor for TIE1-mediated cervical cancer progression." (PMID 38617545, 2024). "Considering that Basigin plays a significant role in TIE1-mediated cervical cancer progression, Basigin inhibitors may be effective for cervical cancer patients with high TIE1 expression." (PMID 38617545, 2024). "To explore the mechanism of action of TIE1 in cervical cancer progression, we examined the potential TIE1-interacting proteins by immunoprecipitation (IP) and liquid chromatography coupled with tandem mass spectrometry (LC‒MS/MS) analysis in the TIE1-overexpressing HeLa cell line." (PMID 38617545, 2024).
cervical cancer (continued). "Previous studies have shown that cervical cancer cells can express Tie-1 at levels similar to ECs, leading to the question of whether Tie-1 cleavage mainly occurs in endothelial cells or in cancer cells." (PMID 34975347, 2021). "However, the role of TIE1 in cervical cancer progression, metastasis and treatment remains elusive." (PMID 38617545, 2024). "However, the role and mechanism of TIE1 in cervical cancer progression remain elusive." (PMID 38617545, 2024). "Furthermore, TIE1 has potential as a novel prognostic factor in cervical cancer." (PMID 38617545, 2024). "In conclusion, TIE1 could stabilize Basigin in cervical cancer." (PMID 38617545, 2024). "Therefore, in this study, we investigated whether serum Tie-1 (sTie-1) is a valuable marker for predicting the progression and prognosis of cervical cancer." (PMID 34975347, 2021). "A question of interest is that of the role of mediating mechanisms in cervical cancer, which may be similar to those seen in inflammation, with tumor conditions potentially leading to Tie-1 extracellular cleavage and activating the ANG/Tie-2 pathway, resulting in tumor angiogenesis." (PMID 34975347, 2021). "Taken together, these findings indicate that TIE1 is an independent prognostic factor for both OS and PFS in cervical cancer patients." (PMID 38617545, 2024). "However, the clinical significance of circulating Tie-1 in cervical cancer remains unclear." (PMID 34975347, 2021). "Here, we uncovered a novel molecular mechanism by which TIE1 promotes cervical cancer progression, independent of TIE2." (PMID 38617545, 2024). "In our previous study, TIE1 was detected by IHC in 80 cervical cancer tissues and 19 normal cervix tissues." (PMID 38617545, 2024). "Although our study did not explore the relationship between TIE1 and cervical cancer chemotherapy resistance, it prompts consideration of whether TIE1-mediated regulation of DNA damage repair also occurs in cervical cancer." (PMID 38617545, 2024).
cholangiocarcinoma (2 papers, 2024). A carcinoma that arises from the intrahepatic biliary tree (intrahepatic cholangiocarcinoma) or from the junction, or adjacent to the junction, of the right and left hepatic ducts (hilar cholangiocarcinoma). "Conversely, higher levels of TIE1 were observed in cholangiocarcinoma (CHOL), head and neck squamous cell carcinoma (HNSC), kidney renal clear cell carcinoma (KIRC), liver hepatocellular carcinoma (LIHC) and stomach adenocarcinoma (STAD) compared to normal tissues." (PMID 38706903, 2024). "In addition to suppressing cholangiocarcinoma cell proliferation, migration, and invasion, menin also suppresses the expression of pro-angiogenic factors such as VEGFA/C, VEGFR2/3, angiopoietins-1/2, and angiopoietin receptors TIE1/2 in a cholangiocarcinoma cell line and tumor xenograft model." (PMID 39336822, 2024).